TNF (tumor necrosis factor)
Diseases named in the same sentence as TNF in open-access papers (continued):
Sharing a sentence is not in itself a finding about the gene and the disease.
colitis (continued). "Based on these features, the histology of colitis in TNF-deficient T/I mice (and TNF-haplo-insufficient T-het/I mice) closely resembled what is typically seen in human UC, while colitis in mice singly deficient in IL-10 more closely resembled that seen in human CD." (PMID 22848611, 2012). "Thus, tissue from DKO mice with colitis showed increased production of pro-inflammatory cytokines compared with mice singly deficient in IL-10, mast cells, or TNF." (PMID 20808919, 2010). "TNF-α production is negatively associated with colitis symptoms in the DSS model." (PMID 19232107, 2009). "The findings indicated that curcumin effectively mitigated weight loss and colon shortening caused by colitis, enhanced the expression of anti-inflammatory factor IL-10 mRNA (p < 0.05), and suppressed the expression of pro-inflammatory factors (IL-1β, IL-6, and TNF-α mRNA; p < 0.05)." (PMID 40724653, 2025). "This is particularly relevant as Gram-negative bacteria, including enterobacteria, are major LPS producers, and their reduction may lower susceptibility to colitis and attenuate inflammatory responses mediated by proinflammatory cytokines such as TNF-α and IL-1β." (PMID 40141446, 2025). "Therefore, combining lactate with an anti-TNF biologic may represent a potential strategy for relieving symptoms and reducing the risk of complications in patients with colitis." (PMID 38474712, 2024). "Consequently, DSS treatment caused an imbalance of the immune cells and colitis inflammation through increased production of TNF-α and IFN-γ, but FAA inhibits the production of these cytokines, regulating intestinal immune cell function and alleviating inflammation." (PMID 38611304, 2024). "This difference may be related to the anti-inflammatory effect of oestrogen, study found that oestrogen decreased the production of macrophage migration inhibitory factor, which affected the susceptibility to inflammation in the colon by reducing the TNF-α and IL-1β production in colitis." (PMID 37907907, 2023). "In addition to being associated with colitis, fatty liver, gout, etc., it is also positively correlated with levels of inflammatory markers (TNF-α, IL-1β, and IL-6)." (PMID 38032532, 2023). "Additionally, the level of IL-1β and TNF-α was also increased in colitis-associated cancer." (PMID 36016583, 2022). "This study indicates that TNF-α antagonists may reduce the risk of colitis-associated CRC." (PMID 35954156, 2022). "An intracerebroventricular injection of anti-TNF-α antibody and minocycline (an inhibitor of microglial/macrophage activation), reversed these findings, which may suggest CNS microglial/macrophage and/or TNF-α involvement in neuroinflammation associated with colitis." (PMID 34983592, 2022). "Also, the alteration of gut microbiota from P. tenera extract effectively alleviated colitis symptoms such as body weight loss, colon length loss, and diarrhea, and also attenuated the mRNA expression of pro-inflammatory cytokines (TNF-α, IL-6, IL-1β, and COX-2)." (PMID 35877732, 2022). "The authors also demonstrated the release of cytokines (e.g., IL-1β, IFN-γ, and TNF-α) from cytotoxic T cells (CTLs) and the high expression of chemokine receptor genes on colitis-associated T cells in patients with irAE colitis, which may be involved in the development of irAE colitis." (PMID 35740355, 2022). "Despite the DSS-colitis is caused through the toxic damage of the intestinal and colonic epithelial cells, the inflammatory reactions ensue after the proinflammatory cytokines (Il-1β, Il-6, TNFα, and INFγ) production by tissue macrophages that seems to play an essential role in the disease process." (PMID 36384756, 2022). "Infliximab may be considered as a therapeutic target for TNFα in colitis-associated CRC." (PMID 34220337, 2021).
colitis (continued). "Colitis can cause intestinal epithelial barrier dysfunction and increase its permeability; furthermore, antigens can enter the intestinal lumen, causing the accumulation of lymphocytes and macrophages and resulting in the release of inflammatory factors and cytokines, such as TNF-α, IL-6, and IL-1β." (PMID 31936300, 2020). "In addition, the DSS-associated colitis immune alterations were also more obvious in the Z5D group compared with the K6D or control groups, as shown by increased serum levels of proinflammation cytokines, such as TNF-α, IFN-γ, and IL-17a (P < 0.05)." (PMID 32670220, 2020). "Interestingly, mice which are lacking the Tnfa gene were no longer susceptible to acute or chronic TNBS-induced colitis whereas mice overexpressing Tnfa were more susceptible to chronic TNBS-induced colitis, suggesting a rather harmful function of TNFα signalling during TNBS-induced colitis." (PMID 30995806, 2019). "The group on high dose vitamin D (D++) developed the most severe colitis as measured by blinded endoscopic (p < 0.001) and histologic (p < 0.05) assessment, weight loss (p < 0.001), drop in serum albumin (p = 0.05) and increased expression of colonic TNF-α (p < 0.05)." (PMID 30065252, 2018). "Moreover, TNF deficient mice were more prone to acute colitis, thus leading to the conclusion that TNF might have protective functions in normal gut homeostasis and intestinal epithelial integrity." (PMID 29321764, 2017). "Thus concurrent production of TNFα and IFNγ by Ndfip1-deficient Th17 cells, coupled with the observed destruction of the colon mucosa, may explain the severe weight loss seen in the colitis model." (PMID 28051111, 2017). "Furthermore, observations that TNF deficient mice were more susceptible to acute DSS colitis have led to the concept that TNF might have protective functions in normal gut homeostasis and intestinal epithelial integrity." (PMID 28413453, 2017). "The results showed that allergen-related colitis was induced in mice as shown by heavy infiltration of inflammatory cells in the colon mucosa, loss of body weight of mice, increases in myeloperoxidase, tumor necrosis factor-α, interleukin-4, OVA-specific IgE in the colon tissue." (PMID 27604348, 2016). "Moreover, Th1 cells produce large amounts of TNF-α and are classically associated with colitis." (PMID 26998523, 2016). "This study describes a novel interaction that links myofibroblasts with these mediators and may partially explain how cross talk interactions initiated by TNF-α may incite both an inflammatory and a cytoprotective response that predisposes to colitis-associated cancer." (PMID 23688423, 2013). "In some tumors associated with chronic inflammation, TNF inhibition may be protective, such as follicular lymphoma, and as demonstrated in a mouse model of dextran sulfate sodium and azoxymethase-induced colitis and colon cancer." (PMID 24225257, 2013). "Moreover, mice given anti-TNF-α were less susceptible to both colitis and colitis-associated CRC." (PMID 23109839, 2012). "Overall, these studies underline the complexity of TNF bioactivity via TNF-R1 or 2 during the onset and perpetuation of intestinal inflammation, which may be affected by different TNF-R expression patterns and distinct colitis models used." (PMID 23285227, 2012). "Similarly, TNF-α signaling seems to be involved in colitis-associated CRC." (PMID 23109839, 2012). "In addition, the fact that infliximab results in a response in some of these patients suggests that HPS may be linked to Crohn's disease, or at least that TNF-a plays a pivotal role in both types of colitis." (PMID 18067668, 2007). "Serum analysis showed that EGT significantly lowered DSS-elevated levels of IL-6, IL-1β and TNF-α, confirming its systemic anti-inflammatory effects in this colitis model." (PMID 41530565, 2026). "Treatments were initiated after colitis was induced (anti-TNF antibody, prednisolone, or anti-IL-23 antibody)." (PMID 42196181, 2026).
colitis (continued). "In a mouse model of chemical-induced colitis, GI-delivery of anti-murine TNF nanobody via live S. boulardii improved both survival and disease severity without causing overt perturbation of microbiome composition." (PMID 41800924, 2026). "An intestinal epithelial cell injury model was established by tumor necrosis factor-alpha (TNF-α) stimulation, alongside a mouse colitis model induced by dextran sulfate sodium (DSS) administration." (PMID 40665732, 2026). "In DSS-induced colitis mice, oral Casein-PE@TNF-Ab markedly increased colon length and suppressed colonic TNF-α, IL-1β, and MPO levels by 82%, 61%, and 62%, respectively, versus DSS." (PMID 41985594, 2026). "To assess the effect of FBT on the inflammatory response in colitis mice, we used ELISA kits to detect the levels of inflammatory factors IL-1β, IL-6, and TNF-α in the serum." (PMID 40238292, 2025). "Other data showed that 20 mg/kg RES supplementation was able to diminish TNF-α level in chronic DSS-induced colitis." (PMID 40565241, 2025). "For example, L. johnsonii can alleviate DSS-induced colitis by down-regulating the IL-17 and TNF signaling pathways." (PMID 41476955, 2025). "In a mouse model of Dextran sodium sulfate (DSS)‐induced colitis, curcumin has been demonstrated to have protective effects through regulation of TNF‐alpha release." (PMID 40589768, 2025). "Inflammation of the colonic mucosa is a key feature of colitis, where the role of pro-inflammatory mediators such as IL-1β, IL-6, IL-23 and TNF-α is well established." (PMID 40943092, 2025). "Kyoto Encyclopedia of Genes and Genomes (KEGG) analysis indicated that EGR1 overexpression significantly affected multiple pathways, of which the TNF-α signaling pathway was closely connected with the macrophage inflammatory response in colitis." (PMID 40904624, 2025). "In the colitis model, combined LCs supplementation significantly suppressed the expression of TNF‐α, CXCL4, and caspase‐3, while enhancing occludin expression, thereby protecting against 5FU‐induced colonic apoptosis and barrier disruption." (PMID 40444121, 2025). "The treatment of the wild-type DSS-induced colitis group improved the inflammatory response by increasing gut–homeostatic cytokines, such as interleukin-10 (IL-10) and tumor necrosis factor-alpha (TNF-α)." (PMID 40872478, 2025). "In summary, we constructed an engineered inflammation‐targeting probiotic EcNΔlpp::A5‐aTN with enhanced colonization and high efficacy of anti‐TNF‐α nanobody secretion, and effectively alleviated colitis in mice." (PMID 41017573, 2025). "It suppressed the pro-inflammatory tumor necrosis factor-alpha (TNF-α) and upregulated the anti-inflammatory interleukin-10 (IL-10), both of which were dysregulated by colitis (p < 0.0001)." (PMID 41465478, 2025). "In an experimental model of colitis, CLA was shown to reduce inflammation caused by DSS and CD4+ by diminishing the production of TNF-α and suppressing NF-κB." (PMID 40806004, 2025). "It has been shown that MOS promotes macrophage polarization to the M2 type by targeting the SIGNR1 receptor in a DSS-induced murine colitis model, which in turn down-regulates the expression of pro-inflammatory factors such as TNF-α and IL-6." (PMID 40732026, 2025). "Findings from previous investigations have shown that the intestinal mucosal barrier was disrupted in rats with experimental colitis when inflammatory factors (such as IL-6, IL-8, IL-1β, and TNF-α) were elevated, leading to intestinal barrier dysfunction." (PMID 40129987, 2025). "Elevated TNF-α levels in colitis also contribute to the disruption of epithelial barrier integrity, proinflammatory activation of macrophages and other immune cells, and progression of tissue damage." (PMID 41515203, 2025). "In the DSS colitis mouse model, liraglutide-treated mice exhibited significantly lower caecal occludin mRNA levels and higher TNF-α mRNA levels compared to controls, while RegIIIβ and IL-33 mRNA levels showed an increased trend." (PMID 40426955, 2025).
colitis (continued). "Growing evidence indicates that during the onset of colitis, the body produces large amounts of pro-inflammatory cytokines (IL-6, TNF-α, IL-1β, etc.), primarily derived from macrophages and neutrophils." (PMID 41008172, 2025). "Research suggests that the active ingredient Renshen in WFC can effectively mitigate colitis by reducing cell infiltration and lowering levels of inflammatory markers such as IL-6 and TNF-α." (PMID 41284643, 2025). "Animal experiments further demonstrate that PMS extracts reduce levels of pro‐inflammatory factors such as IL‐6 and TNF‐α in colitis models." (PMID 40289624, 2025). "Etanercept is FDA approved for the treatment of autoimmune diseases and has previously been validated to treat experimental colitis in rodents due to its cross-reactivity with rat TNFα (57, –59)." (PMID 40366696, 2025). "Mice transplanted with the colitis microbiome showed higher expression of IL-6, IL-1β, and TNF-α in the colon than mice transplanted with the normal mouse microbiome." (PMID 40076732, 2025). "Irisin, a myokine secreted by muscle, has been shown to ameliorate experimental colitis and reduce TNF-α levels in the colon, supporting the notion that muscle mass influences anti-TNF pharmacokinetics." (PMID 40616584, 2025). "A study on TNBS-colitis (equivalent to CD) as a model of Th1 disease showed increased production of TNF-α, IL-1β, and IFN-γ in colonic submucosal macrophages, and OCT treatment reduced all these effects." (PMID 40508145, 2025). "Among other treatments, colitis is treated with biologics inhibiting the proinflammatory cytokine tumor necrosis factor (TNF)." (PMID 40366696, 2025). "Butyrate deficiency in IBD patients links dysbiosis to impaired Treg function; butyrate supplementation reduces inflammation in DSS-colitis models and enhances anti-TNF therapy response." (PMID 41476956, 2025). "For example, administering B. longum expressing a PEP-1-hMnSOD fusion protein in DSS-induced colitis mice reduced inflammatory cytokines (TNF-α, IL-1β, IL-6, and IL-8) and mitigated histological damage in colonic tissues." (PMID 40243712, 2025). "TTM significantly reduced colonic inflammation and the levels of IL-6, IL-1β, and TNF-α in colitis mice." (PMID 40969742, 2025). "Increased colitis severity and stronger T helper 17 (Th17) responses, production of TNF and IFNγ by CD4+ T cells." (PMID 40860650, 2025). "In the context of active colitis, its upregulation likely represents the host’s attempt to counterbalance the overwhelming production of pro-inflammatory cytokines (e.g., TNF-α, IL-6) and to restrain overactive immune cells." (PMID 41517138, 2025). "A recent experimental study found that short-term high-fat diets exacerbate colitis through tumor necrosis factor (TNF)-mediated bile acid tolerance impairment, suggesting that BAs act as “opportunistic pathogens” in the gut." (PMID 40332366, 2025). "Suramin administration decreased the severity of colitis; this effect was supported by decreased serum TNF-α, NETs, PTX3, and MDA levels and suppressed TNF-α and VEGF levels in colonic tissue." (PMID 40428786, 2025). "The elevated levels of IL-1β, IL-23 and TNF-α in colon tissues are often used as a biomarker of the severity of colitis." (PMID 40943092, 2025). "In vivo experiments, using mice with induced colitis, showed only a mild amelioration in clinical signs of colitis, but a significant reduction in total colon weight and colonic mRNA expression of TNF-α and IL-6, compared to the control group." (PMID 40871103, 2025). "TNF-α and NF-κB play crucial roles in the development and progression of colitis as well as the development of colon cancer." (PMID 40607420, 2025). "TNF-α and IL-6 levels were significantly higher in Mcpt-4ΔCre colitis mice compared to control Mcpt-4ΔCre mice." (PMID 40697820, 2025). "Consistent with previous studies, our study also suggests that the gut microbiota can affect the response to anti‐TNF therapy in colitis." (PMID 39739648, 2025).
colitis (continued). "Tfam deficiency, which reduces the synthesis and stabilization of mitochondrial DNA (mtDNA), reduces peripheral T cells but increases IFN-γ- and TNF-α-producing effector CD4 T cells, exacerbating age-associated multimorbidity and DSS-induced colitis." (PMID 41451235, 2025). "In the context of colitis, a large number of macrophages accumulate in the lamina propria near the epithelium and overexpress pro-inflammatory cytokines such as IL-1β and TNF-α, indicating macrophage polarization." (PMID 41008172, 2025). "In murine colitis models, the combination of anti‐TNF‐α therapy with NaCr significantly alleviated colitis progression, improved intestinal barrier function and enhanced plasma crotonyl‐CoA production compared to NaCr treatment alone." (PMID 40650658, 2025). "Once released, the OMVs target to inflammatory macrophages and delivered Cas9 RNPs to disrupt TNF-α expression, resulting in marked alleviation of colitis symptoms in inflammatory bowel disease models." (PMID 41035884, 2025). "Treatment with suramin resulted in a marked decrease in TNF-α levels (40.1 ± 1.9 pg/mL), demonstrating significant attenuation of inflammatory response compared to colitis group (# p < 0.01)." (PMID 40428786, 2025). "The study also is the first time to show that the level of IL‐1β, TNF‐α, and IL‐6 in the serum of colitis mice was greatly decreased by IF." (PMID 39898122, 2025). "Muscadine wine polyphenols were shown to prevent weight loss and colon shortening, downregulate the NF-κB pathway and secretion of IL-1β, IL-6, and TNF-α in the colon of mice with DSS-induced colitis." (PMID 40732952, 2025). "In a previous study, L. gasseri JM1 intake suppressed the expression of inflammatory cytokines such as TNF-α and increased the expression of anti-inflammatory cytokines such as IL-10, thereby alleviating intestinal inflammation in a mouse model of colitis." (PMID 40002326, 2025). "For example, Lactobacillus reuteri engineered to produce histamine has been shown to suppress TNF-α in colitis models by modulating host immune-microbe dialogues." (PMID 41333479, 2025). "Biochemical analysis showed that GPE downregulated the levels of the pro-inflammatory cytokines interleukin-1 (IL-1), IL-6, IL-17, tumor necrosis factor-alpha (TNF-α), and nuclear factor-kappa B (NF-κB), compared to the colitis (AA) group." (PMID 40732258, 2025). "In acetic acid-induced colitis models, G. fisheri reduced TNF-α and IL-1β levels while modulating tight junction proteins." (PMID 40077614, 2025). "In contrast, DSS-induced colitis mice that received TcES exhibited significant decreases in the production of TNF-α, IL-1β, and IL-33, as well as Th17-associated cytokines such as IL-23 and IL-17F." (PMID 40576745, 2025). "To test this, we investigated the impact of celastrol on Tregs both in vitro and in vivo, evaluating its efficacy in HSF1fl/fl-CD4cre mice, and in two murine models of IBD: the adoptive transfer colitis, and TNFΔARE+/- ileitis." (PMID 41594602, 2025). "Colonic tissues from DSS‐induced colitis models exhibited significantly increased TNF‐α, IL‐1β, and IL‐18 levels relative to healthy controls (p < 0.01)." (PMID 40994452, 2025). "In a murine model of acetic acid-induced colitis, pregabalin reduced both macroscopic and microscopic intestinal damage and inflammation, decreasing colonic levels of TNF-α, IL-6, IL-1β, and myeloperoxidase (MPO) activity [DOI: 10.4103/1735-5362.329924]." (PMID 40650291, 2025). "Most importantly, the CD4+Notch2+Foxp3lo T cells in the colitis model mice also expressed membrane−bound TNFα and TGF−β (LAP)." (PMID 40702356, 2025). "In this study, the effect of targeting SLC7 A11 on colitis-related intestinal barrier damage was investigated by incubation with a Caco-2 monolayer membrane supplemented with 1 A4 and TNF-α/IFN-γ." (PMID 40360947, 2025).